DUSP6 (dual specificity phosphatase 6)
Diseases named in the same sentence as DUSP6 in open-access papers (continued):
Sharing a sentence is not in itself a finding about the gene and the disease.
tumor (126 papers, 2005 to 2026). "Previous studies on multiple tumor types have linked high DUSP6 expression to worse prognosis and metastasis." (PMID 41028058, 2025). "Supporting this evidence, we observed that DUSP6 was significantly upregulated in tumor cell lines harboring a KRAS mutation compared to tumor cells driven by other mutations in the CCLE dataset." (PMID 41028058, 2025). "In TAM, in colon cancer cells, PKN2-inducible DUSP6 leads to the suppression of tumor-associated M2 macrophage polarization and tumor growth, through the inhibition of the ERK1/2, IL-4, and IL-10 cascade." (PMID 38139370, 2023). "In fact, DUSP6 is implicated as a tumor suppressor gene in PC and, specifically, its expression is suppressed in MIA PaCa-2 cells through intron 1 hypermethylation." (PMID 34439102, 2021). "High expression of DUSP6 was positively associated with the grade 2/3 tumors (p = 0.0052), lymph node and/or distant metastasis (p = 0.0270), and an advanced tumor/node/metastasis stage (p = 0.0309)." (PMID 32159851, 2020). "Similar data has also implicated DUSP6/MKP-3 as a tumour suppressor in mutant Kras-driven lung tumours, where expression levels showed an inverse relationship with both growth activity and histological grade." (PMID 26791049, 2016). "Consistent with our own data, DUSP4 expression has previously been shown to be increased in pancreatic tumours with K-Ras mutations and DUSP6 expression increased in a variety of tumour types with mutations in Ras or Raf pathway genes." (PMID 20147967, 2010). "Given prior studies implicating DUSP6 in immune cells, its potential role in tumor-associated macrophages also warrants further exploration to deepen our understanding of its contributions to the tumor microenvironment." (PMID 41028058, 2025). "In addition to the usual inducers, protein kinase N2 (PKN2) protein kinase is equally capable of inducing DUSP6 in tumor-associated macrophages, reducing ERK activity and the anti-inflammatory cytokines IL-4 and IL-10." (PMID 38139370, 2023). "In addition, quantification of the percentage of tumour-bearing mice that displayed poorly-differentiated PDAC also shows a significant increase on loss of DUSP6." (PMID 35418690, 2022). "Our data suggest that loss of either DUSP5 or DUSP6, as observed in certain human tumours, including the pancreas, could promote carcinogenesis." (PMID 35418690, 2022). "Indeed, stable expression of DEC1 in oesophageal SCC cell lines upregulates dual-specificity phosphatase 6, a tumour- and cell invasion- suppressor gene that is associated with patient survival in oesophageal SCC." (PMID 21326238, 2011). "Considering that glucose is the primary source of energy for tumor cells in vitro, we sought to delineate how DUSP6 affects glucose metabolism in each cell line and conducted a metabolic assay to measure glycolysis activity in the absence of DUSP6." (PMID 41028058, 2025). "To answer this question, we examined DUSP6 expression in different tumor compartments using GSE9332637." (PMID 41028058, 2025). "Subsequently, we investigated Dusp6 expression in mouse tumor tissue using RNA in situ hybridization (RNA-ISH) technology." (PMID 41028058, 2025). "Overexpression of DUSP6 in A375/211 cells led to the reduction of tumour growth of xenografts in mice." (PMID 40943262, 2025). "Conversely, overexpression of DUSP6 in DUSP6-deficient OC cells significantly reduced ERK1/2 activity and inhibited cell proliferation, anchorage-independent growth, and tumour development in nude mice." (PMID 40943262, 2025). "In agreement with these clinical data, DUSP6 emerged as a key player in cell migration and tumour growth, as well as in the downregulation of several genes involved in epithelial-to-mesenchymal transition (EMT)." (PMID 40943262, 2025). "In vitro and in vivo experiments demonstrated that knockdown of DUSP6 reduces tumor invasion, migration, and proliferation ability while enhancing mitophagy in BC cells." (PMID 40936711, 2025).
tumor (continued). "Considering DUSP6 upregulation in epithelial tumor cells derived from metastatic samples, we aimed to underscore the functional role of this molecule in tumor epithelial cells." (PMID 41028058, 2025). "These in vivo results underscore the pivotal role of DUSP6 in contributing to OCT4-induced tumor growth and distant metastasis." (PMID 41210685, 2025). "In OC, elevated DUSP6 expression correlates with cisplatin resistance by attenuating ERK1/2 signalling as observed in patient tumour samples and in cancer cell lines upon overexpression." (PMID 40943262, 2025). "In vivo, administration of the DUSP1/DUSP6 inhibitor BCI increased ERK1/2 and JNK activation, caused tumour necrosis and fibrosis, and reduced tumour volume in MPNST xenografts established with S462.TY cells or patient-derived cells." (PMID 40943262, 2025). "Previous study has demonstrated that DUSP6 have either inhibitory or promotive effects on tumor progression in different types of malignancies." (PMID 40936711, 2025). "Immunohistochemical examination of Ki67 staining demonstrated that DUSP6 knockdown inhibited tumor cell growth in vivo." (PMID 40936711, 2025). "DUSP6 overexpression not only enhances in vitro cancer cell colony formation and migration but also accelerates tumor growth in vivo." (PMID 41210685, 2025). "The observation that DUSP6 expression is significantly lower in PDAC primary tumor cells is counterintuitive, considering what we observed in bulk RNA-seq datasets." (PMID 41028058, 2025). "Together, these results highlight the complex involvement of DUSP6 in both tumor and immune cell populations, as well as its potential influence on metastasis." (PMID 41028058, 2025). "In the in vivo experiments utilizing a xenograft tumor model of nude mouse with subcutaneously injected T24 cells, both the tumor volume and weight were decreased in the DUSP6 knockdown group compared to the control group." (PMID 40936711, 2025). "To better understand how the glycolytic shift induced by DUSP6 knockdown impacts tumor cell behavior, we revisited our previously conducted functional assays and incorporated 2-DG, a well-established inhibitor of glucose metabolism, into the analyses." (PMID 41028058, 2025). "In the present study, our results show that the knockdown of DUSP6 alleviates not only primary tumor growth but also pulmonary metastasis in NOD/SCID mice bearing OCT4-overexpressing A549 lung tumor xenografts." (PMID 41210685, 2025). "In both cell lines (HT-29) and mice, it emerged that the increased expression of GSDMB and subsequently that of DUSP6 reduced cell proliferation and tumour growth." (PMID 40943262, 2025). "Knockdown of DUSP6 increases levels of insulin growth factor binding protein 7 (IGFBP7), a secreted protein regarded as a tumor suppressor, indicating that DUSP6 regulates IGFBP7." (PMID 41210685, 2025). "Our study contributes to the comprehension of DUSP6 in BC by demonstrating that DUSP6 expression is higher in tumor tissues compared to non-tumor tissues." (PMID 40936711, 2025). "Some lines of evidence suggest a tumor-suppressing role for DUSP6, as observed in aerodigestive tract cancers, where its downregulation correlates with tumor formation and poor survival." (PMID 41210685, 2025). "At leukemia, high DUSP6 can activating Janus kinase 2 (JAK2) signaling pathway to promote tumor progression." (PMID 40936711, 2025). "DUSP6 expression was downregulated in 40% and 75% of tumour specimens of ESCC and NPC, respectively, compared to normal counterparts." (PMID 40943262, 2025). "Utilizing the in silico dataset GSE7172928, we compared DUSP6 expression across a cohort comprising 134 non-tumor tissue samples, 145 primary tumor samples, and 62 metastatic samples derived from various secondary sites." (PMID 41028058, 2025).
tumor (continued). "Lastly, we performed co-expression analysis of DUSP6 and KRT19 and found a 1.8-fold increase in DUSP6 positive cells in PDAC KRT19 positive cells compared to healthy pancreata, confirming DUSP6 upregulation in tumor epithelial cells." (PMID 41028058, 2025). "Similar to our previous results, it also demonstrated a significant elevation in PINK1 and PARKIN expression in tumor tissues subjected to DUSP6 knockdown." (PMID 40936711, 2025). "We observed that DUSP6 was overexpressed in metastatic samples compared to primary tumor samples by leveraging in silico, immunohistochemistry, and multiplex RNAscope analysis." (PMID 41028058, 2025). "Our results confirmed that PDAC tumor cells overexpress DUSP6, suggesting the need for further investigation of its role in tumor development." (PMID 41028058, 2025). "The results demonstrated a reduction in the levels of mTOR phosphorylation, Similarly, in the xenograft tumor samples, the p-mTOR level was found to be reduced in the sh-DUSP6 group." (PMID 40936711, 2025). "First, the relationship between RMC-6236 concentration in tumors (tumor PK) and RAS pathway inhibition, as measured by human DUSP6 levels (tumor PD), in xenograft tumors was investigated by compiling a data set from multiple PK/PD studies on each model." (PMID 38593348, 2024). "Findings also show that exogenous overexpression of DUSP6 increases tumor growth as well as resistance to cisplatin mediated cell death in both in vitro and in vivo experiments." (PMID 38418476, 2024). "In vivo, genetic targeting of DUSP6 reduced tumor growth in brain metastasis model, whereas its pharmacological targeting induced synthetic lethal therapeutic effect in combination with HER2i." (PMID 38886591, 2024). "The expression of genes measured at the end of treatment confirmed that improved tumor control is linked to a stronger inhibition of genes that report on the activity of MAPK signaling (e.g., FOSL1, DUSP6, and SPRY4)." (PMID 39199684, 2024). "At 25 mg/kg, RMC-6236 was able to maintain more than 80% inhibition of pERK levels in tumors up to 24 hours post-dose comparable with the inhibition pattern of DUSP6 levels in tumor lysates." (PMID 38593348, 2024). "In multivariable analysis of high ERBB2 expressing tumors, increase in DUSP6 expression and large tumor size (T4) remained significant independent prognostic factors." (PMID 38886591, 2024). "A single oral dose of 10 mg kg−1 RMC-7977 was sufficient to maximally suppress tumour DUSP6 levels (91%) at 8 h, which partially recovered over 48 h, concordant with the decrease in tumour RMC-7977 concentrations." (PMID 38589574, 2024). "To this end, we quantitated the zebrafish intracranial tumor area derived from GFP + MDA-MB-361 cells transfected prior tumor implantation either with control or DUSP6 targeting siRNA." (PMID 38886591, 2024). "DUSP6 is indicated in clinical cancer progression, and its genetic inhibition prevents tumor cell growth." (PMID 38886591, 2024). "Effective suppression was however seen in BRAFi/RANO responders, but in BRAFi/RANO-progressed tumours DUSP6 expression had fully recovered." (PMID 37563469, 2023). "Frequently upregulated MAPK pathway genes in resistant tumours were apart from DUSP6 different FGFs, MYC, EPHA2, and FOS." (PMID 37604687, 2023). "There are more studies on DUSP6 in oncology, demonstrating that its expression improves tumor proliferation and drug resistance." (PMID 37026010, 2023). "Western blots displayed stronger bands in 2 out of 4 tumour samples, which were also evident in preneoplastic lesions in the case of DUSP6." (PMID 37946160, 2023). "We investigated the expression of DUSP6 by RT‐qPCR in individual tumours from 11 tumour models after 5 days and at the EOT." (PMID 37604687, 2023). "Gene expression analyses, in turn, revealed in agreement with the observed DUSP6 rise in the majority of resistant tumours, that re‐activation of the RAS pathway is critical for developing primary and SR." (PMID 37604687, 2023).
tumor (continued). "The gene DUSP6 has been extensively studied in tumor cells but rarely in hair follicle stem cells (HFSCs)." (PMID 36360210, 2022). "More recently, deletion of Dusp6 has been found to promote intestinal proliferation and to increase tumour burden in ApcMin/+ mice, again suggesting a tumour suppressive function." (PMID 35418690, 2022). "Modest changes in cytoplasmic and total p-ERK levels are also seen on deletion of Dusp6 as manifest by a small but reproducible increase in the p-ERK:p-MEK ratio in PDAC cells derived from KCD6−/− mice compared to those derived from tumours in KC animals." (PMID 35418690, 2022). "Altogether, these results indicate that DUSP6 plays a tumor-suppressive role and acts as an intermediate molecule between ARF6 and ERK1/2 in PDAC cells, thereby forming a positive feedback loop." (PMID 36017891, 2022). "Polysome profiling of KRAS G12D tumor cells indicated that p-eIF2α inhibits DUSP6 at the translational level." (PMID 34330898, 2021). "There are >20 known DUSPs in mammals, of which DUSP6 functions as either an oncogene or tumor-suppressor according to different tumor types." (PMID 34803714, 2021). "Studies have shown that higher levels of DUSP6 expression are seen in relatively inactive tumor cells compared with actively proliferating tumor cells." (PMID 32231719, 2020). "In lung cancer and glioblastoma, research has revealed that the proportion of cell in S phase is decreased and those in G1 phase increased in DUSP6- overexpressing tumor cells." (PMID 32231719, 2020). "It seems likely that DUSP6 expression can be fine-tuned to modulate ERK at different stages of tumor progression and that this ability is lost in TIGAR null cells." (PMID 31983610, 2020). "Some G1 phase predominant DUSP6- overexpressed tumor cells are considered to be cisplatin-resistant." (PMID 32231719, 2020). "One report showed that DUSP6 appears to function as a tumor suppressor in EOC, but our results suggest the opposite effect." (PMID 31164954, 2019). "The role of DUSP6 in cancer is mostly related with the type of tumor, being pro-oncogenic or tumor suppressive." (PMID 31027181, 2019). "All of these genes were upregulated in our H460shDUSP6 depleted cells suggesting DUSP6 is tackling different pathways involved in tumor progression such as EMT, ERK, TGFβ and WNT." (PMID 31027181, 2019). "Similar to DUSP5, DUSP6 is inducible by growth and differentiating agents that activate the ERK1/2 pathway, and DUSP6 is also reported to play a tissue-specific dual tumor suppressive or pro-oncogenic role." (PMID 30866462, 2019). "Our results are consistent with the previously reported findings that demonstrate PUM2 reduces the stability of DUSP6 mRNA in tumor cells." (PMID 30787206, 2019). "We next examined the Fn/c of DUSP6 expression that revealed that DUSP6 is predominantly cytoplasmic in control tumors but becomes nuclear biased in surviving tumor cells following treatment with Abraxane or anti-PD1." (PMID 31238530, 2019). "In general, DUSP6 remains an interesting protein in that it has opposing roles in different tumor types." (PMID 31164954, 2019). "DUSP6 expression correlated with tumor cell survival in response to either chemotherapy (Abraxane) or immunotherapy (anti-PD1)." (PMID 31238530, 2019). "Low expression levels of DUSP6 in NSCLC would affect these pathways by increasing tumorigenicity, cell motility, EMT transition and consequently tumor progression associated with poor prognosis in NSCLC patients." (PMID 31027181, 2019). "We have also studied which parameters related with tumorigenicity and tumor progression would be affected by low expression levels of DUSP6." (PMID 31027181, 2019). "Dusp6 is a negative regulator of tumor cell proliferation, and its expression is significantly decreased in many types of invasive tumor cells." (PMID 30275866, 2018).
tumor (continued). "Tumor-bearing lung tissues from mice expressing EGFR or Kras oncogenes produce higher levels of Dusp6 RNA than do normal lung controls or tumor-bearing lungs from mice with a MYC transgene." (PMID 30475204, 2018). "Here, the authors show that DOT1L inhibition or DUSP6 overexpression in T cells attenuates graft-versus-host disease but retains anti-tumour activity in mouse models." (PMID 29765028, 2018). "The combination of BQ788 with BRAF inhibitor led to a significant reduction in tumour growth, which correlated with strong suppression of DUSP6 expression." (PMID 28606996, 2017). "We further analyzed DUSP6, which is a well-described tumor suppressor engaged in a regulatory loop with ERK1/2." (PMID 28423600, 2017). "Among the top five growth-suppressing genes tested, STARD8 and DUSP6, a commonly known tumor suppressor, arrested cells in G1/G0-phase, while MAPRE3, RPS6KA2 and EMD induced apoptosis." (PMID 28423600, 2017). "We detected an upregulation of Rras, which displays tumor-promoting activity, and a downregulation of Dusp6, which participates in the inactivation of MAP kinases." (PMID 29108266, 2017). "Both DUSP5 and DUSP6/MKP-3 are amongst a subset of genes, which are often upregulated in tumours and cancer cell lines in which Ras/MAPK signalling is activated." (PMID 26791049, 2016). "We must highlight that DUSP1, DUSP4, and DUSP6 have pleiotropic roles as both oncogenes and tumour suppressors in various cancers." (PMID 26859151, 2016). "Initially, the ESCC cell lines and primary tumor specimens were screened, demonstrating that the DUSP6 expression level was downregulated at the mRNA and protein levels in ESCC." (PMID 24260056, 2013). "It should be emphasized that the definition of a tumor suppressor gene is dependent upon cell context, and that whilst DUSP6 has been widely reported as having tumor suppressor function, there are reports in other cell models describing DUSP6 as an oncogene." (PMID 23724103, 2013). "Functionally, DUSP6 has demonstrated suppressive effects in tumor formation and cancer cell mobility in ESCC in previous studies." (PMID 24260056, 2013). "Tissue microarray assays indicated that DUSP6 expression inversely correlated with the histological grade, which suggested that lower DUSP6 expression was involved in tumor progression and differentiation." (PMID 24260056, 2013). "In total, 36.8% (7/19) of the tumor biopsies displayed at least two-fold downregulation of DUSP6 compared with their paired normal counterparts, by qPCR." (PMID 24260056, 2013). "In different types of tumors, DUSP6 have various roles depending on the tumor type and the stage of carcinogenesis." (PMID 24260056, 2013). "qPCR was performed to evaluate the mRNA level of DUSP6 in 19 paired normal and tumor tissues from the same patients." (PMID 24260056, 2013). "DUSP6 exerts apparent tumor suppressive effects and is a strong candidate for a tumor suppressor gene." (PMID 24260056, 2013). "Although we are unaware of any published evidence implicating DUSP6 or SPINT2 as tumor suppressors in B lymphoid malignancies, their expression was found to be increased in our experiments where IL-4 impaired EBV-induced transformation." (PMID 23724103, 2013). "Since the ERK1/2 pathway mediates mitogenic signaling, among other responses, DUSP6 has been proposed as a tumor suppressor." (PMID 22784513, 2012). "Western blot analysis was used to confirm the reduced protein expression of AREG, EREG and DUSP6 in A431 tumour cells stably transduced with AREG-, EREG-, and DUSP6-short hairpin (sh)RNAs." (PMID 22491422, 2012). "Furthermore, we observed a significant increase in DUSP6 expression in epithelial cells throughout tumor progression, and once again, a notable decrease in DUSP6 expression in PDAC primary tumors, followed by upregulation in metastatic samples." (PMID 41028058, 2025). "DUSP6 was again increased in primary tumor lesions and, finally, in liver metastasis samples." (PMID 41028058, 2025).